INS (insulin)
Diseases named in the same sentence as INS in open-access papers (continued):
Sharing a sentence is not in itself a finding about the gene and the disease.
diabetes (continued). "However, whether the deficiency of insulin in patients with type 1 diabetes mellitus affects condylar remodeling during treatment with functional appliances remains unclear." (PMID 25289023, 2014). "In our meta-analysis, we could not obtain information from all studies on the blood pressure, weight status, insulin or diabetes conditions which were main risk factors for dyslipidemia, and lacking of those original data limited our further evaluation of potential interactions." (PMID 24671216, 2014). "Therefore, this may constitute an additional mechanism underlying diabetes (and, more particularly, insulin-induced hypoglycemia)-associated neuronal injury, degeneration, and cognitive impairment." (PMID 25071725, 2014). "Diabetes mellitus (DM) is considered a chronic disease characterized by hyperglycemia resulting from insulin resistance and/or insulin secondary deficiency caused by failure in beta cells (β) pancreatic." (PMID 23878822, 2013). "Inflammation, which is the body's normal response to injury and disease, affects insulin signaling and increases beta-cell death, and markers of inflammation such as raised blood levels of C-reactive protein and interleukin 6 are associated with future diabetes risk." (PMID 23843750, 2013). "Furthermore, depression is associated with physiological abnormalities, including the activation of the hypothalamus-pituitary-adrenal axis, the sympathetic nervous system, and the proinflammatory cytokines, which can induce a resistance to insulin, and thus increase the risk of diabetes." (PMID 23853718, 2013). "A better understanding of the extent of the association of adiponectin with IR in obesity might help clarify mechanisms of insulin sensitivity, which in turn, might be beneficial in identifying preventive approaches to enhance insulin sensitivity and thereby reduce the risk for developing diabetes." (PMID 29755881, 2013). "Diabetes mellitus (DM) is a metabolic disorder characterized by lack or deficiency of insulin secretion or even by the peripheral resistance to it." (PMID 23837632, 2013). "In addition to causing NDM, INS mutations may present acutely after the first 6 months of age and even beyond the age of one year, when monogenic diabetes becomes exceedingly rare." (PMID 24051999, 2013). "Diabetes mellitus (DM) is a serious health problem results from abnormality of carbohydrate metabolism and characterized by absolute (type І) or relative (type ІІ) deficiencies in insulin secretion or receptor insensitivity to endogenous insulin, resulting in hyperglycemia." (PMID 23834750, 2013). "The observation of increased cancer risk with obesity and diabetes has led to the somewhat more hopeful speculation of potential therapeutic benefit of insulin-sensitizing drugs with the major clinical outcome of lowering systemic insulin levels." (PMID 23573093, 2013). "However, in three mouse diabetes models of insulin action deficiency, including streptozotocin-induced diabetes and liver insulin-receptor knockout, the expression of PGC-1α was strongly induced, which could lead to increased Sepp1 expression." (PMID 23760059, 2013). "Diabetes mellitus (DM) is a chronic disease associated with abnormal and constant high blood glucose (hyperglycemia) that results from defects in insulin secretion, action, or both." (PMID 24298552, 2013). "However, because combination therapy with GLP-1 RAs and basal insulin improves glycaemic control, reduces body weight and improves cardiovascular risk factors it may lead to reduction in costly complications of diabetes." (PMID 23061470, 2013). "A study that evaluated glucose tolerance and plasma insulin concentrations in more than 1400 young adults (26 to 32 years old) who had grown up in the city of Delhi, India, found an association between thinness in infancy and the presence of impaired glucose tolerance or diabetes in young adulthood." (PMID 23476780, 2013).
diabetes (continued). "Thus, interventions, such as the one used in this study, that target weight loss and increase total adiponectin levels may improve insulin sensitivity and reduce the risk of diabetes for overweight individuals." (PMID 29755881, 2013). "The effect of exercise training in the reduction of fat infiltration in the skeletal muscles could be considered as an additional benefit towards the improvement of insulin resistance, and possibly lowering the risk for the early development of diabetes mellitus." (PMID 24024727, 2013). "In addition, there are a growing number of patients with T1DM and MS who appear to be at increased risk of cardiovascular mortality and development of diabetes related complications, a greater need for higher insulin doses, and multifactorial intervention, thus, more aggressive treatment." (PMID 23956744, 2013). "Diabetes mellitus (DM) characterized by hyperglycemia is a metabolic disorder of carbohydrate, fat, and protein, as a consequence of relative or absolute deficiency of insulin secretion, insulin action, or both." (PMID 24250711, 2013). "Diabetes mellitus (DM), resulting from a deficiency in insulin secretion or its action, is a metabolic disorder accompanying chronic complications such as micro vascular damage, nerve damage, and atherosclerosis." (PMID 24195646, 2013). "In addition, the precise mechanism of how physical activity acts to reduce the risk of type 2 diabetes mellitus, such as through altered insulin sensitivity or altered insulin production, is still unknown." (PMID 24010994, 2013). "While these concerns may be valid, patients also have inaccurate beliefs about insulin therapy, including the idea that insulin causes late-stage diabetes complications and is an indication of imminent deterioration and death, or is a result of patients’ failure to take good care of themselves." (PMID 22313123, 2012). "In addition, in patients undergoing renal transplantation, pretransplant diabetes may be masked by diminished insulin metabolism associated with kidney dysfunction." (PMID 22830041, 2012). "Type 1 diabetes mellitus (DM) is characterized by autoimmune aggression against pancreatic beta cells resulting in absolute deficiency of insulin secretion." (PMID 22442700, 2012). "This is suggested to modulate the cellular response to reactive oxygen species, and could be particularly relevant to pancreatic β-cell function since redox changes are implicated both in the normal physiology of insulin secretion and in diabetes pathophysiology." (PMID 24970137, 2012). "The use of herbal medicines for the treatment of diabetes mellitus has gained importance throughout the world and there is an increased demand to use natural products with antidiabetic activity due to the side effects associated with the use of insulin and oral hypoglycemic agents." (PMID 23056144, 2012). "However, in our cross-sectional observations on the Cherokee children and adolescents we were limited to investigating association of HDL apoC-III with the pre-diabetes phenotype manifesting as obesity associated with insulin resistance progressing to a decline in insulin levels." (PMID 22898077, 2012). "Furthermore onset of obesity before age 21 years compounds diabetes risk and plays a role in causing insulin resistance mediated in part by increased free fatty acids and their deposition in liver and muscle resulting in resistance to insulin’s action on glucose lowering." (PMID 22898077, 2012). "Therefore, we were unable to determine whether impaired insulin action, particularly insulin resistance, could mediate the associations between low serum amylase and diabetes and metabolic syndrome." (PMID 22748134, 2012). "Indeed, diabetes-associated disruption between insulin activity and glucose metabolism results in decreased cerebral blood flow and oxidative glucose metabolism (which may also arise from the impaired blood-brain glucose transport)." (PMID 22500228, 2012).
diabetes (continued). "Type 1 diabetes mellitus (DM) is characterized by autoimmune aggression against pancreatic beta cells resulting in absolute deficiency of insulin secretion, and by its association with certain high-susceptibility HLA alleles." (PMID 22442700, 2012). "The analysis on the decision tree confirmed that treatment success among pregnant women with diabetes and mild hyperglycemia was associated with cost reduction, regardless of management method (inpatient or outpatient) and treatment type (diet or diet + insulin)." (PMID 22344355, 2012). "However, other typical defects of β-cells with known association to diabetes of general forms remain uncharacterized in this model of β-cell dysfunction; these include oxidative stress and abnormalities in glucose-stimulated insulin secretion (GSIS) and β-cell survival." (PMID 22509386, 2012). "Diabetes mellitus (DM) is a group of complex multisystem metabolic disorders due to a deficiency in insulin secretion caused by pancreatic β-cell dysfunction and/or insulin resistance in liver and muscle." (PMID 22143698, 2012). "Taken together, our findings provide a mechanistic foundation for a link between diabetes and AD by demonstrating that insulin deficiency may change APP processing to favor β-amyloidogenesis via the translational upregulation of BACE1 in combination with elevations in its substrate, APP." (PMID 22403710, 2012). "It was previously associated to insulin sensitivity, glucose uptake, and insulin secretion, and, in this study, data suggest that the polymorphism may increase susceptibility to chronic metabolic conditions such as diabetes in the Brazilian population." (PMID 23243416, 2012). "Thus, protein-energy malnutrition early in life may result in a diminished reserve for insulin production, which in turn may predispose to glucose intolerance or even manifest diabetes during conditions of increased insulin demand." (PMID 22754473, 2012). "Given the higher insulin levels and better glucose clearance in Wdr13 gene deficient mice, we propose that this protein may be a potential candidate drug target for ameliorating impaired glucose metabolism in diabetes." (PMID 22715406, 2012). "In the present study, diabetes was induced by Alloxan, a diabetogenic drug that induces the production of reactive oxygen species (ROS) that accumulate in the pancreatic islets causing an irreversible lesion of the cells responsible for insulin synthesis, the β cells." (PMID 23024779, 2012). "It is possible that more intensive use of insulin therapy could result in improved glycemic control in these populations, but an associated increase in culturally-appropriate diabetes education and support would need to be a key component of that management strategy." (PMID 22455801, 2012). "We have shown that insulin in dried blood spots is stable and can be reliably quantified on a very large-scale with modest infrastructure, making the method useful for population-based studies of insulin resistance, diabetes and cardiovascular risk in a variety of settings." (PMID 23056434, 2012). "Since TWEAK inhibits the activation of PI3K/Akt pathway, it is likely that TWEAK might also be causing muscle atrophy in the settings of diabetes and starvation where drop in insulin levels and inhibition of PI3K/Akt pathway are the major mechanisms of muscle loss." (PMID 22082477, 2012). "Since some of these injuries may constitute the underlying mechanisms of brain dysfunction associated with several pathologies (e.g., diabetes, aging and age-related diseases, as Alzheimer's disease (AD)), next, we will discuss the effect of insulin under such pathologies." (PMID 22500228, 2012). "However, this high glycaemic food may cause fluctuations in blood glucose and insulin levels which over time are associated with gain in weight and increased risk of heart disease and diabetes." (PMID 22106751, 2011).
diabetes (continued). "Colonic fermentation of undigested dietary fibers with the production of SCFA has been proposed as one of the potential mechanisms that may explain improved insulin sensitivity and reduced diabetes risk in subjects consuming high fiber diets including diets high in cereal fibers." (PMID 22177085, 2011). "The emerging research on colorectal cancer risk for people with diabetes suggests that diabetic patients with poor glycemic control may have even higher risk because they exhibit high levels of circulating insulin and IGF-1 and are often receiving multiple treatments." (PMID 21672406, 2011). "However, insulin resistant states such as obesity or diabetes are often associated with impaired insulin signaling, which may limit the efficacy of such drugs." (PMID 21886789, 2011). "Diabetes mellitus (DM) is a chronic metabolic disorder characterized by hyperglycemia caused by abnormal insulin production, insulin resistance or often both." (PMID 24250392, 2011). "Potentially, this may be because the presence of the A allele has been associated with conditions detrimental to health such as diabetes, coronary artery disease, severe hypertension and alcohol consumption whereas the GG genotype has been associated with lower fasting insulin levels." (PMID 21595954, 2011). "Thus, the use of PTP1B inhibitors that strengthen insulin signalling may prevent at least some of the problems associated with diabetes and hopefully, the development of AD." (PMID 21294893, 2011). "Therefore, in this epidemiological study, we investigated whether low serum amylase was associated with the pathogenesis of impaired insulin action: metabolic syndrome (MetS) and diabetes." (PMID 21496338, 2011). "Hence, screening early morning fasting FFA or insulin may be an effective strategy in early detection of subject with high risk for development of diabetes." (PMID 21479217, 2011). "The original report of mitochondrial dysfunction associated with diabetes measured ATP turnover rate averaged over 30–150 min of euglycaemic hyperinsulinaemia while subsequent studies compared the later effects (120–350 min) of insulin stimulation of ATP turnover rate." (PMID 20623795, 2010). "Furthermore, a shortage of plasma insulin and low glucose tolerance, resulting in a serious inability to lower blood glucose, will cause insulin resistance, which is the key symptom underlying the potential development of diabetes." (PMID 23554650, 2010). "Decreased insulin sensitivity at the cellular level is also a natural consequence of aging that can, independent of adiposity, subject the elderly population to the higher risk of developing diabetes; and therefore affect the association of measures of adiposity with diabetes." (PMID 20459710, 2010). "Applying these methods to examine the insulin producing beta-cell autoantigen specific T cell responses, we observed little difference between autoimmune diabetic patients and healthy individuals, suggesting a more subtle association between diabetes status and peripheral autoreactive T cells." (PMID 20634998, 2010). "Telomere length might be affected by several biological and lifestyle factors, including body mass index (BMI), smoking, homocysteine levels, cardiovascular disease risk factors, insulin levels or resistance, diagnosis of diabetes, sleep duration, or physical inactivity." (PMID 20520834, 2010). "The postural fall of blood pressure may be unreliable as in people with diabetes it varies throughout the day, being linked to the timing of insulin injections and patients with fluid retention may have extensive autonomic damage but without postural hypotension." (PMID 19178728, 2009). "Whether or not the diabetes-decreased GLUT4 translocation to the plasma membrane was simply a result from insulin signaling deficiency or was an impairment of contraction-mediated GLUT4 translocation involved still needs to be clarified since diabetes also reduced ventricular contractility." (PMID 19706162, 2009).
diabetes (continued). "However a recent comprehensive analysis of the islet and beta cell development revealed that the cause of diabetes in Perk deficient mice is due to failure to expand beta cell mass and defects in beta cell development and insulin secretion during the critical fetal and neonatal periods." (PMID 19732428, 2009). "The present data, in conjunction with the prior population-based studies suggesting a role for the diabetes-associated SLC30A8 polymorphism in insulin secretion or action, raise the question of whether SLC30A8 risk alleles directly impact ZnT8 expression level in vivo." (PMID 19479076, 2009). "Taken together, these findings suggest that visfatin could play a role in the association between obesity and diabetes mellitus, and because of correlation with high insulin levels in LGA group, LGA neonates should be examined closely for insulin resistance in future." (PMID 23675145, 2009). "Therefore, the present study was done to investigate the relationship between paternal insulin sensitivity and the growth parameters of the foetus to determine a genetic link between poor early growth and the increased risk of type 2 diabetes mellitus in later life." (PMID 20062558, 2009). "Moreover, SNP rs3781638 showed significant associations with increased OGTT-derived insulin sensitivity (p<0.0021 after adjustment for gender, age, BMI, and family history of diabetes) and correspondingly decreased HOMA-IR (p≤0.0015 after analogous adjustment)." (PMID 19088850, 2008). "Since, polymorphic variants (C and F alleles) favor higher PAI-1 levels and also overexpress PAI-1 in response to insulin, TNFα and TGFβ; it may imply an enhanced risk of suffering various conditions, such as atherosclerosis, cancer, diabetes, wound healing failure, among other diseases." (PMID 18312663, 2008). "Furthermore, insulin-deficient patients with diabetes have lost the ability to modulate either insulin or glucagon in response to hypoglycaemia and depend instead on autonomic activation, subjective awareness and adrenaline to defend against severe hypoglycaemia." (PMID 18215172, 2008). "Consistent with selective β cell ablation in STZ-diabetic pigs, insulin mRNA by RT-PCR was significantly decreased (p<0.0001), somatostatin and pancreatic polypeptide transcript levels were unaltered, while glucagon mRNA showed the characteristic increase associated with diabetes (p<0.0001)." (PMID 18320053, 2008). "Both health care providers and patients perceive insulin therapy in type 2 diabetes mellitus (DM) as being associated with several barriers." (PMID 19902051, 2008). "Thus the lack or the shortageof the insulin production by the pancreas immediately causes metabolicdisorders, that is, hyperglycemia or high blood glucose concentration, thuseventually resulting in diabetes." (PMID 18437199, 2008). "The enhanced willingness of those offered the option of inhaled insulin treatment to change to a more appropriate therapy increases the potential for achieving improved glycemic control and reducing complications, associated morbidity, premature mortality, and increased cost of diabetes." (PMID 16901335, 2006). "Insulin signaling abnormalities could be the underlying mechanism affecting the outcome of Alzheimer's disease; insulin resistance and disordered degradation of amyloid seem to link diabetes mellitus with Alzheimer's disease." (PMID 17096857, 2006). "Finally, although the polymorphisms of INS have been studied for their roles in diabetes and obesity, this is the first published report on the association between the INS gene and risk of cancer." (PMID 12610512, 2003). "Insulin administration will lower a child’s elevated blood sugar value to a normal range from an elevated range that is characteristic of diabetes." (PMID 41597086, 2026). "From a pathophysiological perspective, the relationship between diabetes and physical activity is based on the beneficial effects of exercise on glucose metabolism and insulin sensitivity." (PMID 41602802, 2026).